RSF1 (remodeling and spacing factor 1)
Description:
Regulatory subunit of the ATP-dependent RSF-1 and RSF-5 ISWI chromatin-remodeling complexes, which form ordered nucleosome arrays on chromatin and facilitate access to DNA during DNA-templated processes such as DNA replication, transcription, and repair. Binds to core histones together with SMARCA5, and is required for the assembly of regular nucleosome arrays by the RSF-5 ISWI chromatin-remodeling complex. Directly stimulates the ATPase activity of SMARCA1 and SMARCA5 in the RSF-1 and RSF-5 ISWI chromatin-remodeling complexes, respectively. The RSF-1 ISWI chromatin remodeling complex has a lower ATP hydrolysis rate than the RSF-5 ISWI chromatin-remodeling complex. The complexes do not have the ability to slide mononucleosomes to the center of a DNA template. Facilitates transcription of hepatitis B virus (HBV) genes by the pX transcription activator. In case of infection by HBV, together with pX, it represses TNF induced NF-kappa-B transcription activation. Represses transcription when artificially recruited to chromatin by fusion to a heterogeneous DNA binding domain.
Synonyms: Rsf-1; HBXAP; XAP8; p325
Tractability: PROTAC: UniProt records ubiquitination sites on it; ubiquitination databases record sites on it; its protein half-life has been measured.
Gene: Protein-coding gene on chromosome 11 (77,660,009 to 77,820,869, reverse strand). Ensembl gene ENSG00000048649.
Subcellular location: Nucleus
Subcellular location (Human Protein Atlas): Nucleoplasm
Pathways (Reactome):
Cell Cycle: Deposition of new CENPA-containing nucleosomes at the centromere
Gene Ontology:
Molecular function: ATP hydrolysis activity; histone binding; histone octamer slider activity; protein binding
Biological process: chromatin organization; chromatin remodeling; DNA-templated transcription initiation; negative regulation of DNA binding; negative regulation of DNA-templated transcription; nucleosome assembly; positive regulation of DNA-templated transcription; positive regulation of viral transcription; regulation of DNA-templated transcription; heterochromatin formation
Cellular component: nucleoplasm; nucleus; RSF complex
Genetic constraint (gnomAD): Loss-of-function variants: 10 observed, 115.05 expected, observed/expected ratio (o/e) 0.0869, 90% interval 0.053 to 0.15. The upper end of that interval is the gene's LOEUF score, 0.15, which puts it in group 1 of 6, group 1 being the genes least tolerant of losing a copy. Missense variants: 1,429 observed, 1,613.2 expected, observed/expected ratio (o/e) 0.89, 90% interval 0.85 to 0.93. Synonymous variants: 530 observed, 565.16 expected, observed/expected ratio (o/e) 0.94, 90% interval 0.87 to 1.01.
Homologues: Orthologues: chimpanzee RSF1 (99% identical), macaque RSF1 (98% identical), rabbit RSF1 (89% identical), guinea pig RSF1 (88% identical), pig RSF1 (86% identical), mouse Rsf1 (84% identical), rat Rsf1 (83% identical), tropical clawed frog rsf1 (54% identical), zebrafish rsf1b.1 (44% identical), zebrafish rsf1b.1 (16% identical), Caenorhabditis elegans dpff-1 (4% identical), Drosophila melanogaster d4 (4% identical), and 1 more. Paralogues in human: KAT6B (15% identical), KAT6A (13% identical), KAT7 (7% identical), PHF10 (7% identical), DPF3 (6% identical), DPF2 (6% identical), KAT5 (6% identical), DPF1 (5% identical), KAT8 (5% identical).
Diseases named in the same sentence as RSF1 in open-access papers:
RSF1 is named in the same sentence as 41 diseases in open-access papers, as found by Europe PMC text mining. Sharing a sentence is not in itself a finding about the gene and the disease. The quoted sentences say what the papers report.
ovarian carcinoma (16 papers, 2008 to 2025). A malignant neoplasm originating from the surface ovarian epithelium. "Although RSF1 has been implicated in breast and ovarian cancers, our findings provide the in vitro and in vivo evidence of its oncogenic role in ESCC." (PMID 40862741, 2025). "For instance, in ovarian cancer, elevated RSF1 levels have been implicated in resistance to paclitaxel, a commonly used chemotherapeutic drug, thereby reducing its efficacy." (PMID 40558555, 2025). "The results shown that gene MZB1, HSF1, PIK3R4, PSMB9, RSF1 and SPI1were significantly overexpressed in ovarian cancer cells SKOV-3." (PMID 40424327, 2025). "In ovarian cancer, miR-150-5p regulates the RSF1/NF-κB signaling pathway, increasing sensitivity to paclitaxel." (PMID 40558555, 2025). "In ovarian cancer, the interplay between Rsf-1 and SMARCA5 contributes to tumor cell survival and growth." (PMID 34736517, 2021). "Knockdown of PRLB has been identified at least partly to improve the sensitivity of ovarian cancer cells to paclitaxel by inhibiting miR-150-5p to further inhibit the activation of RSF1/NF-κB signalling." (PMID 34147108, 2021). "A strong correlation between high levels of RSF1 in ovarian cancer and increased expression of NF-κB-targeted genes involved in evasion of apoptosis (CFLAR, XIAP, BCL2, and BCL2L1) and inflammation (PTGS2) has also been found." (PMID 34147108, 2021). "PRLB inhibitors or RSF1 inhibitors must play an important role in increasing the sensitivity of ovarian cancer to paclitaxel." (PMID 34147108, 2021). "RSF1-overexpressing paclitaxel-resistant ovarian cancer cell lines were found to express elevated levels of genes regulated by NF-κB." (PMID 32867128, 2020). "RSF-1 (also called HBXAP) was previously found as the key cancer-driving gene within the defined 11q13.5 genetic amplicon in ovarian cancers, which can be supported by several other studies in other cancer types." (PMID 29480799, 2018). "It did contain the RSF1 gene, whose overexpression and amplification in ovarian cancer is a marker of poor prognosis." (PMID 24367492, 2013). "We applied the proposed method to yeast cell cycle microarray data and Rsf-1-induced ovarian cancer microarray data." (PMID 18837990, 2008). "The first data set is a yeast cell cycle microarray data set with 104 well known cell cycle-related genes; the second is a remodeling and spacing factor 1 (Rsf-1) induced microarray data set from a profiling study of ovarian cancer." (PMID 18837990, 2008). "Rsf-1 ectopic expression dramatically increased paclitaxel resistance in ovarian cancer cells." (PMID 37322027, 2023). "RSF1 was further identified as a target of miR-150-5p in ovarian cancer cells." (PMID 36105363, 2022). "RSF1 can activate the NF-κB signaling pathway in ovarian cancer cells." (PMID 36105363, 2022). "Hence, lncRNA PRLB enhanced paclitaxel resistance via targeting miR-150-5p/RSF1/NF-κB in ovarian cancer cells." (PMID 36105363, 2022). "RSF1-transduced dendritic cells induced a CTL response to produce IFN-γ and IL-12 against ovarian cancer cells in vitro, suggesting that RSF1-transduced dendritic cells may be a potential adjuvant immunotherapy." (PMID 34736517, 2021). "Recently, RSF1 gene amplification was found in ovarian cancer." (PMID 34147108, 2021). "Therefore, it is likely that either amplification or overexpression of EMSY and RSF1 may contribute to taxane resistance in ovarian cancer." (PMID 29707144, 2018). "Region 20q13.12, previously identified in other ovarian tumors, was amplified in our cohort, along with other genes that have previously found amplified in ovarian cancer such as CCNE1, ERBB2, RSF1 and deleted genes like BRCA18,22." (PMID 37400526, 2023). "SNF2H can only bind with cyclin E1 in RSF1 expression-induced SKOV3 ovarian cancer cells, implying that cyclin E1 binds with SNF2H through direct binding with RSF1." (PMID 34147108, 2021).
ovarian carcinoma (continued). "Thus, the result from the current immunohistochemistry study further supports the biological link between Rsf-1 upregulation and DDR in ovarian cancer tissues either by aberrant chromatin remodeling or by oncogene/replicative stress." (PMID 22028712, 2012).
breast carcinoma (8 papers, 2013 to 2025). "The overexpression and amplification of RSF1 are reported in many cancers, including breast cancer, and are associated with poor overall survival, advanced clinical features, and drug resistance." (PMID 41278204, 2025). "Our most significant AM association was upstream of RSF1, a gene implicated in ovarian and breast cancers (rs11604207, p = 1.6×10−06)." (PMID 23424626, 2013). "The most significant SNP in both models was rs11604207 (Model 1: p = 1.59×10−06; Model 2: p = 1.82×10−06), which is located upstream of RSF1, a gene encoding a chromatin remodeling protein implicated in ovarian and breast cancers." (PMID 23424626, 2013). "High Rsf-1 expression is associated with breast cancer subtype and poor prognosis." (PMID 28391240, 2017). "Our findings align with studies in other cancers, such as ovarian and breast cancers, where elevated RSF1 levels drive tumor growth, resistance to therapy, and poor prognosis." (PMID 40558555, 2025). "CCND1 gene amplification was observed in 8.7% and RSF1 in 6.8% of these patients, preferentially in estrogen receptor-positive breast cancers." (PMID 24367492, 2013). "Based on our findings, further study of the role of RSF1 in breast cancer biology, and, specifically, response to anti-estrogen therapies, is warranted." (PMID 24367492, 2013). "Unlike CCND1 amplification, RSF1 amplification may predict for outcome in high-risk premenopausal breast cancer patients treated with adjuvant tamoxifen." (PMID 24367492, 2013). "Our results suggest that amplification of RSF1 – but not that of the gene encoding for cyclin D1 – may be a candidate predictive biomarker for adjuvant tamoxifen benefit in this high-risk early breast cancer population." (PMID 24367492, 2013). "The EMSY, PAK1, RSF1, and GAB2 genes are located within the 11q13/14 breast cancer amplicon." (PMID 28391240, 2017). "However, determining the direct contribution of EMSY to breast cancer has been difficult because the gene resides within the 11q13-11q14 locus, containing a cassette of genes, including several known and potential breast cancer drivers (CCND1, PAK1, and RSF1)." (PMID 24582497, 2014). "RSF1 is also faced with a similar issue due to the lack of bromodomain or catalytic domains, and further study on RSF1 interaction partners in breast cancers may potentially give therapeutic benefits." (PMID 41278204, 2025). "Further investigations into the negative predictive value of 11q14 in placebo-controlled studies, such as the NSABP B-14, are required to confirm the role of RSF1 amplification as a biomarker of negative predictive value for tamoxifen benefit in the adjuvant setting in early breast cancer." (PMID 24367492, 2013).
ovarian serous carcinoma (6 papers, 2010 to 2021). "For example, using genome-wide DNA copy number analysis, investigators have identified amplification in a genomic locus (ch11q13.5) harboring a chromatin remodeling gene, RSF1, encoding Rsf-1 in high-grade ovarian serous carcinomas." (PMID 22969800, 2012). "Our results suggest that the DNA damage response is common in high-grade ovarian serous carcinomas, especially those with Rsf-1 overexpression, suggesting that Rsf-1 may be associated with DNA damage response in high-grade serous carcinomas." (PMID 22028712, 2012). "RSF1 is amplified and overexpressed in 25% of high-grade ovarian serous carcinomas and codes for remodeling and spacing factor 1 (Rsf-1), a chromatin remodeling protein involved in the regulation of gene expression and cellular proliferation." (PMID 24367492, 2013). "RSF1, a chromatin-remodeling gene, was identified as a potential oncogene in ovarian serous carcinoma." (PMID 20932292, 2010).
cervical cancer (5 papers, 2018 to 2025). A primary or metastatic malignant neoplasm involving the cervix. "For example, in cervical cancer, miR-503-5p enhances cisplatin resistance by downregulating RSF1 expression, while miR-185-5p also influences cisplatin resistance and angiogenesis by regulating RSF1." (PMID 40558555, 2025). "RSF1 is upregulated in cervical cancer, and RSF1 siRNA combined with radiation can inhibit cell viability, redistribute the cell cycle and induce apoptosis of HeLa and SiHa cell lines." (PMID 34147108, 2021). "RSF-1 expression was significantly increased in cervical cancer tissues than in CIN and normal tissues." (PMID 29480799, 2018). "Our study therefore aims to identify potential effects of RSF-1 overexpression in cervical cancer by immunohistochemistry." (PMID 29480799, 2018). "With solid evidence showing the involvement of RSF-1 in cancer development, however, there are few reports regarding its roles in cervical cancer." (PMID 29480799, 2018). "Our data suggest RSF-1 overexpression a prognosis marker for cervical cancer patients with poor clinical outcomes." (PMID 29480799, 2018). "Western blot also demonstrated robust RSF-1 expression in these two cervical cancer cell lines (right)." (PMID 29480799, 2018). "To assess the possibility of using RSF-1 as a therapeutic target, we detected its mRNA expression levels in cervical cancer cell lines (HeLa and SiHa) using 293T cells as the control, a well known non-tumorigenic cell line." (PMID 29480799, 2018). "Further, linc00958/RSF-1 downregulation or miR-185-5p upregulation could alleviate the cisplatin resistance and tube formation in cervical cancer cells via AKT1/GSK3β/VEGFA pathway." (PMID 36056431, 2022). "Targeting RSF-1 gene expression and the pathway it controls may provide new therapeutic avenues for treating advanced stage cervical cancer that are refractory to conventional therapy." (PMID 29480799, 2018). "In conclusion, our data suggest that chromatin remodeling factor, RSF-1, participates in the tumor progression of cervical cancer and could be considered as a prognostic marker for predicting clinical outcome." (PMID 29480799, 2018). "Finally, human cervical cancer HeLa cells were used as an experimental model to verify the efficacy of anti- RSF-1 therapy for treating cervical cancer." (PMID 29480799, 2018). "In addition, overexpression of RSF-1 in cervical cancer predicts a shorter survival time, suggesting its prognostic value for clinical application." (PMID 29480799, 2018). "RSF1 inhibitors may be a promising way to develop new radiosensitizers for cervical cancer." (PMID 34147108, 2021). "linc00958/miR-185-5p/RSF-1 modulates cisplatin resistance and angiogenesis through AKT1/GSK3β/VEGFA pathway in cervical cancer." (PMID 36056431, 2022). "Furthermore, the upregulation of miR-185-5p or RSF-1 downregulation inhibited the cisplatin resistance in SiHa/DDP cells, suggesting that linc00958 mediated the cisplatin resistance via miR-185-5p/RSF-1 axis in cervical cancer cells." (PMID 36056431, 2022). "To know whether RSF-1 overexpression determines drug sensitivity in cervical cancer cells, we estimated the IC50 of paclitaxel treatment in HeLa cells with or without RSF-1 down regulation." (PMID 29480799, 2018).
nasopharyngeal carcinoma (5 papers, 2019 to 2024). A carcinoma arising from the nasopharyngeal epithelium. "Further study found that RSF1 overexpression in nasopharyngeal carcinoma CEN-2 cells increases the expression of the NF-κB targeted gene SURVIVIN, thereby enhancing paclitaxel resistance by activating NF-κB." (PMID 34147108, 2021). "In nasopharyngeal carcinoma, NEAT1 enhanced the cisplatin resistance by targeting Rsf-1 and Ras-mitogen-associated protein kinase signaling pathway." (PMID 30894512, 2019). "RSF-1, remodeling and spacing factor 1, engaged in DNA damage repair and cell apoptosis, was reported to reduce cisplatin resistance in malignant melanoma and nasopharyngeal carcinoma." (PMID 36056431, 2022). "In addition, downregulation of lncRNA NEAT1 could inhibit cisplatin resistance by suppressing RSF-1 through competitively binding to let-7-5p in nasopharyngeal carcinoma." (PMID 36056431, 2022).
ovarian tumors (3 papers, 2018 to 2023). "In the library prepared from ovarian tumor tissue, 5 clones with coding sequences were identified using the HMGB1 bait (C1QA, DAG1, RPL29, RSF1, TGM2), and 6 (COMMD1, MIEN1, PCBP1, TBC1D25, ZFR, ZNF428) were identified with the HMGB2 bait." (PMID 32867128, 2020). "In their cohort of ovarian tumors analyzed, EMSY was more frequently amplified than RSF1 (16% vs 12%), yet both genes were co-amplified in about 65% of cases." (PMID 29707144, 2018).
esophageal squamous cell carcinoma (2 papers, 2025). Esophageal squamous cell carcinoma (ESCC) is a type of esophageal carcinoma (EC) that can affect any part of the esophagus, but is usually located in the upper or middle third. "Elevated RSF1 expression has been reported across various cancer types and is often associated with poor clinical outcomes; however, its role in esophageal squamous cell carcinoma (ESCC) has not been previously explored." (PMID 40862741, 2025).
Fanconi Anaemia (2 papers, 2014 to 2024). "RSF1, a new player in the cellular responses to DNA double-strand breaks, sequentially recruits centromeric histone-like proteins and DNA repair proteins from the Fanconi anaemia pathway." (PMID 24800743, 2014). "Specifically, RSF1 recruits two centromeric histone-like proteins that in turn promote mono-ubiquitination and recruitment to sites of damage of FANCD2 and FANCI—two proteins that belong to the Fanconi anaemia pathway." (PMID 24800743, 2014).
gynecological cancers (2 papers, 2018 to 2020). "In agreement with previous studies on other gynecological cancers, such as ovarian high-grade serous carcinoma and ovarian clear cell carcinoma, up-regulation of RSF-1 is related to bigger tumor sizes, poor cytopathological characteristics, advanced stages and nodal metastasis." (PMID 29480799, 2018).
lung carcinoma (2 papers, 2020 to 2023). "successfully deleted a panel of oncogenes in lung cancers, including those encoding for epidermal growth factor receptor (EGFR), CD38, focal adhesion kinase (FAK), NESTIN, remodeling and spacing factor 1 (RSF1), and catenin delta 2 (CTNND2)." (PMID 37356052, 2023).
lymph node metastasis (2 papers, 2016 to 2024). "It was also found that a high expression of RSF1 was associated with lymph node metastasis in ovarian clear cell carcinoma." (PMID 27148394, 2016). "The remodeling and spacing factor 1 (RSF1) protein has also been suggested to contribute to cancer progression, as its expression levels have been found to increase in more advanced pathological stages, lymph node metastasis, higher Gleason scores, and increased tumor cell proliferation." (PMID 38622735, 2024).
malignant melanoma (2 papers, 2022 to 2025). "The expression levels of the RSF1 gene were positively correlated with C1GALT1 gene expression levels in all cancer types, including melanoma." (PMID 40548474, 2025).
osteosarcoma (2 papers, 2014 to 2021). A usually aggressive malignant bone-forming mesenchymal neoplasm, predominantly affecting adolescents and young adults. "We validated the chicken Atm–Rsf1 complex by co-immunoprecipitation of human RSF1 with human ATM using U2OS osteosarcoma cells." (PMID 24800743, 2014). "XIST is another potential biomarker of osteosarcoma which has been reported to modulate osteosarcoma proliferation and invasion through miR-320b/RAP2B, miR-193a-3p/RSF1, miR-21-5p/PDCD4, and miR-195-5p/YAP axis." (PMID 33639865, 2021).